STAT3 (signal transducer and activator of transcription 3)
Diseases named in the same sentence as STAT3 in open-access papers (continued):
Sharing a sentence is not in itself a finding about the gene and the disease.
tumor (continued). "Because STAT-3 target genes encode many factors that activate STAT-3 in the immune cells, possibly a feed-forward mechanism for activation of STAT-3 in both the tumor cells and the immune cells within the tumor microenvironment is initiated as proposed by Kortylewski." (PMID 19900287, 2009). "Given the correlation between dysregulated STAT3 activation and tumor cell survival, we wanted to determine whether inhibition of Src and STAT3 activity in OSA cell lines affected their capacity to proliferate and survive." (PMID 19284568, 2009). "STAT3 (the signal-transducer and activator –of transcription 3) is thought to play an important role in both tumorigenesis and tumour progression, and is often constitutively activated in tumour cells." (PMID 18827820, 2008). "Understanding how IL-6 and other soluble factors are involved in this paracrine activation of STAT3 via the tumor microenvironment may provide new therapeutic insight to treat breast carcinomas and other cancers with elevated p-STAT3 and IL-6 levels." (PMID 18939993, 2008). "Understanding how IL-6 and other soluble factors may lead to STAT3 activation via the tumor microenvironment will provide new therapeutic regimens for breast carcinomas and other cancers with elevated p-STAT3 levels." (PMID 18939993, 2008). "Understanding which soluble factors are involved in this paracrine signaling and how these factors lead to STAT3 activation via the tumor microenvironment will provide new therapeutic targets for breast carcinomas and other cancers with elevated p-STAT3 levels." (PMID 18939993, 2008). "Therefore, we analyzed the EGFR and STAT3 proteins in the A2780 cDDP tumor xenografts from mice treated with NCX-4040 and/or cisplatin." (PMID 18302761, 2008). "Interestingly, IL-6 is activated in ICU patients and has been reported to increase mir-21 in tumour cell lines mediated via STAT3." (PMID 18997871, 2008). "However, little has been known about the activation of STAT3 in regards to the other components within the tumor microenvironment, including the interaction between tumor cells and surrounding fibroblasts and epithelial cells." (PMID 18939993, 2008). "TUNEL was also used to examine the apoptotic tumor cells after STAT3 decoy ODN treatment in vivo." (PMID 17683579, 2007). "Further, STAT3 has anti-apoptotic functions in a range of tumour cell lines." (PMID 17295906, 2007). "The rapid activation of STAT3 signaling pathways may explain the ability of IL-6 to rescue cells from TGF-β1-mediated growth inhibition, since STAT3 is known to mediate proiliferative and anti-apoptotic signaling in normal and tumor cells." (PMID 17324269, 2007). "Furthermore, it has been reported that IL-6 was able to induce degradation of Cdc25A by STAT3 activation, which would form a repressor complex with the Rb tumour suppressor to occupy the Cdc25A promoter and block its induction." (PMID 17987036, 2007). "Among these candidate cytokines, IL-6, which activates Stat3 through the gp130/Jak pathway, is notable for its pleitrophic tumor-promoting activities, including anti-apoptotic, pro-invasive, and immune-stimulatory effects attributable to the activation of Stat3 target genes." (PMID 17531096, 2007). "In addition, when we stress the cells using apoptosis inducers the blockade of STAT3 does increase tumour cell apoptosis." (PMID 16804520, 2006). "STAT3 suppresses expression of pro-inflammatory mediators in tumor cells." (PMID 16001973, 2005). "It has been established that abnormal activation of STAT molecules (especially involving Stat3 and Stat5) stimulates cell proliferation and prevents apoptosis in a number of human tumours, including leukaemia, multiple myeloma, breast, prostate and non-small-cell lung cancer." (PMID 15316561, 2004).
tumor (continued). "For example, targeted depletion of M2 TAMs to restore CD8+T cell cytotoxicity in advanced OC; inhibiting the IL-6 pathway to attenuate STAT3-mediated tumor growth promotion; and modulating DCs migration to increase intratumoral distribution, which may enhance anti-tumor immunity." (PMID 41601649, 2026). "Since aberrant STAT3 activation is widely implicated in epithelial tumorigenesis, including cutaneous SCC, and its constitutive phosphorylation upregulates pro-survival and pro-proliferative genes, these changes are mechanistically consistent with delayed tumor development." (PMID 41596287, 2026). "In addition, targeting STAT3 increases the HPV-specific anti-tumor adaptive immune response." (PMID 41749853, 2026). "Additionally, IL-35/STAT3/PAX5/BCL6 signaling-driven transcriptional dysregulation in naïve B cells could impair their differentiation into anti-tumor effector cells." (PMID 41522514, 2026). "Future investigations should characterize macrophage subsets (such as iNOS/CD86 versus Arg1/CD206) using flow cytometry or multiplex immunostaining to determine whether macrophage-derived cytokines contribute to IL-6/STAT3 signaling during UVB-driven tumor promotion." (PMID 41596287, 2026). "Its deficiency activates the c-Myc/IL-6/STAT3 signaling pathway, leading to PD-L1 upregulation and enhanced M2 macrophage polarization, while restoring LOC339059 expression could inhibit this process and exert a tumor suppressor effect." (PMID 41550841, 2026). "At the same time, in the RLS40 model, DNase treatment resulted in a decrease in the mRNA levels of pro-tumor phenotype markers (Ccl17, Il10) and an increase in the mRNA levels of anti-tumor phenotype markers (Icam1, Tnfa, Vegfr1), as well as cell mobilization genes (Ern1, Stat3)." (PMID 40867260, 2025). "Moreover, Th9/Th22 correlation was negative in EOCRC cohort, suggesting that IL-9-driven inflammatory signals may help restrain IL-22-mediated STAT3 activation and tumor-promoting self-renewal pathways." (PMID 41425582, 2025). "However, once tumors were established, Stat3 deletion proved integral to reducing tumor growth." (PMID 40356899, 2025). "Interestingly, integrin β3, the ITGB3 gene product, and its functional heterodimer integrin αvβ3 have also been reported to drive tumor initiation, drug resistance, and metastasis, similarly to STAT3,9–11 suggesting an important JAK/STAT3/integrin β3 signaling axis in PDAC." (PMID 40701148, 2025). "Therefore, we propose that SESN1&2 may act as tumor suppressors in lung and other cancer types by suppressing aberrant STAT3 activation, protecting against uncontrolled cell proliferation, and maintaining cell death." (PMID 39985075, 2025). "Moreover, the combination of JAK1/2 inhibitors with TKI therapy and the combined use of ALK and STAT3 inhibitors can regulate the immune response and restore the sensitivity of tumor cells to treatment, thereby overcoming the resistance driven by AST and improving the treatment outcome." (PMID 40568576, 2025). "Within this inflammatory milieu, STAT3 plays a key role in skewing macrophage polarization toward the M2 phenotype, which, although traditionally viewed as anti-inflammatory, contributes to tumor immune evasion by producing immunosuppressive cytokines such as IL-10 and TGF-β." (PMID 40704145, 2025). "Therefore, STAT3 can promote metastasis but may suppress tumor growth depending on tumor stage/environment." (PMID 41463281, 2025). "These AGEs activate inflammatory signaling cascades such as the NF-κB and STAT3 pathways, resulting in increased production of pro-inflammatory cytokines (e.g., interleukin-6 and tumor necrosis factor-alpha) that induce DNA damage, inhibit apoptosis, and promote tumor progression." (PMID 41479778, 2025).
tumor (continued). "Therefore, silibinin offers significant promise as a therapeutic agent in reversing tumor drug resistance through various mechanisms, including inhibition of drug efflux pumps, modulation of cell adhesion, and regulation of key signaling pathways like STAT3." (PMID 40490812, 2025). "Additionally, FABP5 is closely associated with tumor-related signaling pathways, such as PPAR-γ, NF-κB, and IL-6/STAT3, and may promote tumor progression and metastasis through these pathways." (PMID 40717587, 2025). "STAT3 plays a critical oncogenic role by maintaining persistent activation, often through Tyr705 phosphorylation, which upregulates anti-apoptotic genes such as Bcl-xL, survivin, and Mcl-1, thereby promoting tumor cell survival, proliferation, and therapeutic resistance." (PMID 41210679, 2025). "Inflammation and signaling pathways: activation of inflammation-related pathways such as IL6, STAT3, and NF-κB in cancer tissues correlates with the presence of specific flora (e.g., Proteobacteria), which may promote tumor progression through ROS and DNA damage." (PMID 40297591, 2025). "Importantly, we demonstrated that this tumor-driven proliferation of THP1 cells could be suppressed by the STAT3 inhibitor STAT3-IN-12." (PMID 41514627, 2025). "STAT-3, which is a transcription factor activated through cytokine signaling, induces the differentiation of respective T-helper lineages depending on the context; its polarization towards tumor regulation attenuates DNA repair processes, leading to genomic instability." (PMID 41376623, 2025). "However, tumor cells often suppress these negative regulators, allowing sustained STAT3 activation." (PMID 40166646, 2025). "Additionally, prior studies have suggested that STAT3 may influence the expression of DNA repair genes and modulate the tumor microenvironment to promote therapy resistance." (PMID 40723906, 2025). "Moreover, we observed reduced expression of Ki‐67 (a tumor proliferation marker) and STAT3 in piR‐RCC overexpression or stattic treatment groups alone compared to the control group, with even lower expression in piR‐RCC overexpression and stattic combination treatment group." (PMID 40411401, 2025). "Consequently, JAK/STAT3 pathway inhibitors may suppress tumor cell proliferation and promote antitumor immunity." (PMID 40487371, 2025). "Activation of IL-6/STAT3 impairs dendritic cell antigen presentation, reduces T cell responses, and promotes the accumulation of immunosuppressive cell populations such as regulatory T cells and myeloid-derived suppressor cells, fostering an immunosuppressive tumor microenvironment." (PMID 41409248, 2025). "IL‐12‐hyperexpressing monocytes exhibit suppressed phosphorylation of STAT3 (p‐STAT3) and diminished c‐Myc signaling activity, a molecular reprogramming that drives macrophage polarization toward proinflammatory M1 states while exerting tumor‐suppressive effects on HCC progression." (PMID 40529613, 2025). "Consequently, the repression of RBM47 may result from a combination of a decrease of FOXA1 expression and the activation of the RBM47-repressing factors, such as STAT3, during tumor progression." (PMID 41335176, 2025). "Furthermore, STAT3 facilitates the interaction between cancer cells and the host immune system, amplifying cachexia’s systemic effects by fostering immunosuppression and promoting tumor progression." (PMID 40704145, 2025). "Furthermore, STAT3 promotes tumor invasion by upregulating proteins involved in EMT." (PMID 40699663, 2025). "Furthermore, enhancing tumor apoptosis through ACSL4 inhibition and targeted acetylation of signal transducer and activator of transcription 3 (STAT3) was associated with a reduction in mitochondrial membrane PLs, providing a critical strategy to overcome cancer cell chemoresistance." (PMID 41288931, 2025).
tumor (continued). "In combination, the tumor-promoting pro-inflammatory activity as well as the immunosuppressive activity may represent crucial molecular processes underlying the potent oncogenicity of combined HH/GLI and IL6/STAT3 signaling." (PMID 39962447, 2025). "Moreover, increased UCK2 levels in HCC have been shown to promote tumor growth and metastasis by activating critical oncogenic signaling pathways, including STAT3, Wnt/β-catenin, and EGFR-AKT, whereas UCK2 knockdown significantly suppresses tumor cell proliferation." (PMID 41357200, 2025). "Targeting NRN1 could offer a novel therapeutic approach to inhibit STAT3-driven tumor growth." (PMID 41425077, 2025). "In addition, the anti-tumor activity of COC-mediated p-STAT3 inhibition was investigated." (PMID 40027184, 2025). "Targeting STAT3 in these cells could reduce tumor recurrence and improve patient outcomes." (PMID 40075607, 2025). "Hence, we speculate that EUDAL/EGFR/STAT3 signaling-induced autophagy may lead to drug resistance in these tumor cells." (PMID 40940319, 2025). "Modulation of histone lactylation and pharmacological inhibition of STAT3 can restore immune sensitivity in B7-H3-mediated resistance, promisingly highlighting potential of combining targeted or epigenetic therapies with immunotherapeutic approaches to overcome tumor immune evasion." (PMID 40801642, 2025). "In addition, NPC tumor supernatants may promote the up-regulation of PD-L1 expressed on VECs by activating the NF-κB and STAT3 signaling pathways." (PMID 40000620, 2025). "The NF-kB/IL-6/STAT3 cascade may also be useful to explain the anticancer activity of auranofin, as NF-kB, IL-6, and STAT3 are central players linking chronic inflammation to cancer by driving tumor initiation and subsequent growth and metastasis." (PMID 40333653, 2025). "Upregulated STAT3 expression in the peripheral rim and invasive margin (but not tumour core) relative to non-diseased brain tissues, may hint at STAT3-associated pro-invasive and immune microenvironment modulatory effects as reported across pan-cancer studies." (PMID 40617935, 2025). "Furthermore, it inhibited phosphorylated STAT3, thereby disrupting pro-tumor signaling pathways." (PMID 41007800, 2025). "In addition to tumor-intrinsic effects, STAT3 also exerts immunosuppressive functions." (PMID 40867898, 2025). "Importantly, STAT3 can be activated in a wide range of human tumors, including solid and hematological tumors, and its overexpression has been observed in various patient-derived tumor tissue samples." (PMID 40118821, 2025). "This chronic inflammatory state generates reactive oxygen species (ROS), causing DNA damage that may promote tumorigenesis, and activates a series of signaling pathways (such as NF-κB and STAT3), promoting tumor cell survival and proliferation while resisting apoptosis." (PMID 41573649, 2025). "However, additional combination of MUC1 LCP-mRNA with an anti-CTLA4 antibody was needed to enhance CD8+ T cell recruitment, inhibit the tumor-promoting STAT3 pathway, and further enhance anti-tumor responses in the murine triple negative breast cancer cells, in vivo." (PMID 41012179, 2025). "Moreover, FOSL1 is involved in other important signaling pathways that affect tumor progression, such as the interleukin-6/signal transducer and activator of transcription 3 (IL-6/Stat3) pathway, the Wnt-β-catenin pathway, and other major carcinogenic pathways." (PMID 40821785, 2025).
tumor (continued). "STAT3 is frequently overexpressed and constitutively activated in OSCC, driving tumor growth and stemness through the regulation of genes associated with self-renewal, epithelial-to-mesenchymal transition (EMT), and the suppression of anti-tumor immune responses." (PMID 40140827, 2025). "Additionally, ZFP14 mitigated the STAT3‐enhanced tumour metastasis." (PMID 39936533, 2025). "Furthermore, it inhibited the migration and invasion abilities of GBM cells and improved the inflammatory microenvironment by inhibiting the NLRP3 inflammasome and the JAK2/STAT3 signaling pathway, which is known to play a role in promoting inflammation and tumor progression." (PMID 41009025, 2025). "Together, our findings highlight the potential of neutrophil-specific STAT3 inhibition as a promising strategy for harnessing myeloid cells in cancer immunotherapy and provide new insights into reprogramming the innate immune compartment to strengthen anti-tumor immunity." (PMID 40885734, 2025). "Given that the inhibition of STAT3 activity modulates neutrophil tumorigenic potential, we were next interested in whether the targeted silencing of STAT3 in neutrophils in vivo would suppress tumor growth." (PMID 40885734, 2025). "Furthermore, activating the JAK2/STAT3 pathway could induce programmed death-ligand 1 (PD-L1) expression, indicating that downregulating STAT3 could activate tumor immunity by inhibiting PD-L1 expression." (PMID 41280323, 2025). "The dual STAT3/CDK2 inhibitor Nifuroxazide suppressed STAT3 phosphorylation, thereby blocking the release of Palbociclib-induced senescence-associated secretory phenotype (SASP) and alleviating SASP-mediated remodeling of the tumor microenvironment, metastasis, and drug resistance." (PMID 41228247, 2025). "Through the JAK-STAT pathway (specifically STAT3), IL-10 signaling inhibits dendritic cell maturation, reduces pro-inflammatory cytokine production by macrophages and other cells, and attenuates T-cell activation, thereby effectively suppressing anti-tumor immunity." (PMID 41006647, 2025). "The observed decrease in STAT3 expression in E7-transfected cells in our study demonstrates the multifaceted action of this viral protein, which not only promotes immune evasion but may also support tumor growth." (PMID 40733498, 2025). "For instance, scutellarin was found to disrupt tumor-associated angiogenesis by reducing transcription factor AP-1, while chrysin contained remarkable anti-angiogenesis properties through inhibiting VEGF/VEGFR2 expression and the phosphorylation of factors, e.g., JAK1 and STAT3 in HUVECs." (PMID 39860127, 2025). "Therefore, CRP may also contribute to tumor progression by inducing the production of IL‐6 by macrophages, followed by STAT3 activation in tumor tissues." (PMID 39564003, 2024). "The stronger binding affinity of LOC344887-v2 to p-STAT3 compared to LOC344887-v1 suggests that variant-specific interactions may play a critical role in the regulation of STAT3 signaling, which is known to drive various aspects of tumor biology, including proliferation, survival, and metastasis." (PMID 39664573, 2024). "Several oncogenic signaling pathways, such as Akt/mTOR, JAK/STAT3, and EGFR/MAPK, or the loss or silencing of PTEN, ALK, and EGFR, are involved in the regulation of PD-L1 transcription, potentially leading to the upregulation of PD-L1 expression in tumor cells." (PMID 38762484, 2024). "Among these processes, Liu and colleagues have proven that the Wnt/β-catenin pathway may stimulate the phosphorylation of signal transducer and activator of transcription 3 (STAT3), which has been shown to be associated with tumor growth in and a poor prognosis for OSCC patients." (PMID 39204206, 2024).